TRIM37 (tripartite motif containing 37)
Diseases named in the same sentence as TRIM37 in open-access papers (continued):
Sharing a sentence is not in itself a finding about the gene and the disease.
lung carcinoma (7 papers, 2020 to 2025). "The metastatic ability of lung cancer cells was inhibited by the knockdown of TRIM37, as Akt activity was suppressed; thereafter, lung cancer cells were prone to apoptosis." (PMID 35163097, 2022). "TRIM37 contributes to the aggressiveness by activating NF-κB signaling pathway in non–small-cell lung cancer cells." (PMID 36923153, 2022). "In addition, lung cancer cells were less likely to migrate and proliferate after the suppression of TRIM37 either through EMT process inhibition of oncogenic transcriptional factor downregulation." (PMID 35163097, 2022). "Considering the functional characteristics of CDC20, CDC45, TRIM37 and MMP9, it is not surprising that BARX1 promotes cellular proliferation, migration and invasion of lung cancer cells by transactivating CDC20, CDC45, TRIM37 and MMP-9 expression." (PMID 37587140, 2023). "TRIM37 promoted lung cancer progression by activating the PI3K/AKT and NF-κB pathways, and TRIM37 suppression resulted in significant decreases in tumorigenesis in vivo." (PMID 35163097, 2022). "We therefore conclude that BARX1 transactivates CDC20, CDC45, TRIM37 and MMP-9 genes, thereby promoting cellular proliferation, migration and invasion of lung cancer cells due to the functional roles of these genes in cell-cycle progression, DNA synthesis and their association with carcinogenesis." (PMID 37587140, 2023).
neuroblastoma (7 papers, 2020 to 2026). Neuroblastoma (NB) is the most common solid, extracranial childhood tumor. "We show here that chromosome 17q/TRIM37 gain is a defining feature of high-risk neuroblastoma and renders patient-derived cell lines hypersensitive to the novel PLK4 inhibitor RP-1664." (PMID 42288516, 2026). "To define the frequency of TRIM37 copy number gain in high-risk neuroblastoma we analyzed whole genome sequencing data from the Gabriella Miller Kids First (GMFK) cohort of primary diagnostic neuroblastomas (dbGaP Study Accession: phs001436.v1.p1)." (PMID 40766251, 2025). "We show here that chromosome 17q/TRIM37 gain is a pathognomonic feature of high-risk neuroblastoma and renders patient-derived cell lines hypersensitive to the novel PLK4 inhibitor RP-1664." (PMID 40766251, 2025). "After extensive quality control to remove cases with low tumor content and/or low sequencing coverage, all 42 high-risk neuroblastomas showed evidence for 17q gain (37 with segmental 17q gain, 5 with whole chromosome 17 gain), with all but one sample showing gain at the TRIM37 locus." (PMID 40766251, 2025). "Finally, TRIM37 copy number and mRNA levels were directly associated and neuroblastoma showed the highest median mRNA expression level of all human cancers." (PMID 40766251, 2025). "The genomic locus harboring TRIM37 is amplified in several cancers—including neuroblastoma, breast, liver, and kidney tumors —and elevated TRIM37 levels contribute to chemoresistance." (PMID 41446055, 2025). "We observed high sensitivity to RP-1664 across a panel of nine neuroblastoma cell line models carrying TRIM37 gain, with a median viability IC50 of 35nM (range 26–109nM)." (PMID 40766251, 2025). "Due to near universal prevalence of TRIM37 gain in neuroblastoma, we sought to define the potency of RP-1664 in preclinical models of this disease." (PMID 40766251, 2025). "We now demonstrate that 17q/TRIM37 gain is more prevalent than previously reported, suggesting that selection of neuroblastoma patients based on TRIM37 copy number status may not be necessary." (PMID 40766251, 2025). "We deployed a panel of fifteen human neuroblastoma xenograft models (5 CDX and 10 PDX), all showing 17q gain including the TRIM37 locus (no xenograft models without 17q gain were available)." (PMID 40766251, 2025).
pancreatic cancer (6 papers, 2018 to 2023). "The knockdown of TRIM37 in mouse pancreatic cancer cell line Pan18 and human pancreatic cancer cell lines, PANC-1 with KRAS mutation and BxPC-3 with wild-type KRAS, resulted in a significant reduction in the viability of pancreatic cancer cells." (PMID 35163097, 2022). "In the wound healing assay, the migration area of pancreatic cancer cells at different time points was dramatically decreased when TRIM37 was knocked down compared with WT and shLuc control groups." (PMID 35163097, 2022). "To examine the impact of TRIM37 on the progression of pancreatic cancer in vivo, we injected mouse pancreatic cancer cells containing shTRIM37 or shLacZ plasmid or WT into syngeneic mice." (PMID 35163097, 2022). "A previous study showed that TRIM37 mediated chemoresistance and stemness maintenance in pancreatic cancer cells by ubiquitination of PTEN." (PMID 34743406, 2022). "In contrast to the effect of TRIM37 knockdown in pancreatic cancer on CXCL-1 and G-CSF, there was an increase in the production of IL-12, MCP-1, and MIP-1α." (PMID 35163097, 2022). "In conclusion, our study demonstrated that knockdown of TRIM37 reduced the viability, migration, and invasion of pancreatic cancer cells both in vitro and in vivo and regulated cytokine production." (PMID 35163097, 2022). "The number of colonies formed by pancreatic cancer cells following TRIM37 knockdown was reduced; additionally, these colonies had a smaller size than that of the control colonies." (PMID 35163097, 2022). "After confirming the protein expression level in various cell lines, the MTT assay was conducted to explore the downstream effect of TRIM37 knockdown on pancreatic cancer viability." (PMID 35163097, 2022). "Our results show that TRIM37 promoted pancreatic cancer cell migration, invasion, and clonogenicity." (PMID 35163097, 2022). "Our in vitro data showed that TRIM37 promoted pancreatic cancer viability, migration, invasion, and clonogenicity." (PMID 35163097, 2022). "Numerous in vitro experiments have been conducted to explore the effect of TRIM37 knockdown on the development and progression of pancreatic cancer." (PMID 35163097, 2022). "Although all injected pancreatic cancer cells were capable of developing tumors, it was observed that the silencing of TRIM37 in mouse pancreatic cancer cells significantly suppressed the tumor growth." (PMID 35163097, 2022). "A decrease in the expression of TRIM37 in both mouse and human pancreatic cancer cells resulted in decreased invasion and migration ability of cells." (PMID 35163097, 2022). "Compared to WT and shLuc control cells, a decrease in the number of colonies was observed in TRIM37 knockdown pancreatic cancer cells." (PMID 35163097, 2022). "In summary, the data obtained from both in vitro and in vivo experiments indicate that TRIM37 plays an oncogenic role in the progression of pancreatic cancer." (PMID 35163097, 2022). "In the present study, we observed that TRIM37 knockdown resulted in reduced proliferation, clonogenicity, migration, and invasion ability of pancreatic cancer cells." (PMID 35163097, 2022). "Collectively, these findings suggest a key role of TRIM37 in promoting pancreatic cancer progression." (PMID 35163097, 2022). "We examined the effect of TRIM37 knockdown on pancreatic cancer cells’ migration and invasion ability using wound healing assay and Matrigel invasion assay." (PMID 35163097, 2022). "Our results showed that TRIM37 knockdown significantly inhibited the viability of pancreatic cancer cells." (PMID 35163097, 2022). "We previously showed that TRIM37 is overexpressed in and promotes the proliferation and invasion of pancreatic cancer (PC)." (PMID 33194618, 2020). "TRIM37 overexpression promoted the migration and proliferation of pancreatic cancer cells in vitro by way of activation of the beta-catenin/TCF complex." (PMID 30586926, 2018).
pancreatic cancer (continued). "Both studies indicate an instrumental role of TRIM37 in cancer and its promising role as a target for hepatic and pancreatic cancer treatment." (PMID 30586926, 2018). "Colony formation assay and cell migration assay were performed to study the functions of TRIM37 in pancreatic cancer cells, and TRIM37 expression was increased in pancreatic tumor compared to normal tissue." (PMID 30586926, 2018). "Our data showed that TRIM37 promoted pancreatic cancer cell migration and invasion." (PMID 35163097, 2022). "In this study, we investigated the role of TRIM37 in regulating pancreatic cancer progression." (PMID 35163097, 2022). "The protein expression of TRIM37 in pancreatic cancer cell lines was detected by western blotting." (PMID 35163097, 2022). "Since these pathways are involved in cell proliferation and survival, we examined whether TRIM37 facilitates pancreatic cancer cell proliferation." (PMID 35163097, 2022). "Furthermore, the overexpression of TRIM37 enhanced the growth and migration of pancreatic cancer cells by activating the β-catenin/TCF signaling pathway." (PMID 35163097, 2022). "Similarly, the results of the invasion assay indicated that the number of invading TRIM37 knockdown pancreatic cancer cells was significantly reduced." (PMID 35163097, 2022). "Using multivariate Cox regression analysis, we detected eight optimal ubiquitination-related genes (RNF7, NPEPPS, NCCRP1, BRCA1, TRIM37, RNF25, CDC27, and UBE2H) and then used them to construct a risk model to predict the prognosis of pancreatic cancer patients." (PMID 33414811, 2020). "Therefore, understanding the mechanism by which TRIM37 facilitates pancreatic cancer progression could provide insight into potential targets for the development of an effective therapeutic strategy against this malignant disease." (PMID 35163097, 2022). "Thus, we examined the effect of TRIM37 knockdown on cytokine production in pancreatic cancer cells." (PMID 35163097, 2022). "Therefore, we proposed that TRIM37 greatly contributes to pancreatic cancer cell proliferation." (PMID 35163097, 2022). "Therefore, we investigated the effect of TRIM37 on pancreatic cancer progression in vivo." (PMID 35163097, 2022). "In this study, we aimed to investigate whether TRIM37 could facilitate pancreatic cancer progression by modulating cell proliferation, clonogenicity, migration, invasion, and the tumor immune microenvironment through the regulation of cytokine production in pancreatic cancer cells." (PMID 35163097, 2022). "Similarly, the survival and migration of pancreatic cancer cells were promoted by TRIM37." (PMID 35163097, 2022). "Furthermore, TRIM37 in pancreatic cancer cells could modulate the immune profile by increasing the proportion of immunosuppressive macrophages in the tumor microenvironment to promote tumor aggressiveness." (PMID 35163097, 2022). "However, the role of TRIM37 in pancreatic cancer progression remains unclear." (PMID 35163097, 2022). "Moreover, in mice bearing TRIM37 knockdown pancreatic cancer cells, the proportion of CD11b+F4/80+MHCIIlow immunosuppressive macrophages was significantly reduced in tumor milieu, which might be due to the regulatory role of TRIM37 in cytokine production by pancreatic cancer cells." (PMID 35163097, 2022).
breast tumors (5 papers, 2008 to 2025). "It has been also shown that TRIM37 overexpression sensitizes breast tumors to centrosome loss." (PMID 38324534, 2024). "An exception is found in a subset of breast tumors and derived cell lines that downregulate RING1B and amplify the gene encoding Tripartite Motif containing 37 (TRIM37), an unrelated ubiquitin ligase." (PMID 34968234, 2019). "PLK4 inhibition might be a useful therapeutic strategy, especially for TRIM37 amplified breast tumors, as a stand-alone modality or in combination with other treatment modalities to synergize their anticancer effects and/or overcome resistance." (PMID 41092110, 2025).
gastric cancer (5 papers, 2020 to 2025). A primary or metastatic malignant neoplasm involving the stomach. "As an oncogenic protein in gastric cancer, TRIM37 was expressed at higher levels in human gastric cancer tissues than in peritumoral tissues." (PMID 39768197, 2024). "In vitro experiments using MKN45 and AGS cells demonstrated that elevated TRIM37 correlated with aggressive characteristics, including invasion and advanced stage in gastric cancer, while TRIM37 knockdown had the opposite effects." (PMID 39768197, 2024). "Mechanistically, TRIM37 can facilitate the invasion and metastasis of gastric cancer cells by increasing the expression of Smad-interacting protein 1 (SIP1), a transcription factor that regulates EMT." (PMID 39768197, 2024). "Conversely, silencing of TRIM37 had been proved to have the opposite effects, suggesting its potential significance in gastric cancer progression via SIP1." (PMID 39768197, 2024).
Infertility (4 papers, 2016 to 2025). "Consistent with infertility as shown in Mulibrey nanism patients and Trim37-deficient mice, our in-house developed strains carrying FINmajor variants have shown the infertility phenotype at 8 weeks." (PMID 37528081, 2023). "Trim37−/− mice recapitulate several features of the human MUL disease and thus provide a good model to study disease pathogenesis related to TRIM37 deficiency, including infertility, non-alcoholic fatty liver disease, cardiomyopathy and tumorigenesis." (PMID 27044324, 2016). "The most consistently seen phenotypes in Trim37−/− mice were infertility and the associated hormonal findings, whereas there was more variability in the other phenotypes observed." (PMID 27044324, 2016). "The same infertility problems and organ size are found in the murine model as both male and female TRIM37 KO mice are infertile." (PMID 30586926, 2018). "Female Trim37−/− mice were able to become pregnant at the age of 6 weeks, but females older than that were infertile." (PMID 27044324, 2016). "The infertility phenotype is recapitulated in Trim37−/− mice." (PMID 27044324, 2016). "Constant findings that were seen in all Trim37−/− mice were infertility and a small skull size." (PMID 27044324, 2016).
osteosarcoma (4 papers, 2020 to 2023). A usually aggressive malignant bone-forming mesenchymal neoplasm, predominantly affecting adolescents and young adults. "Increased activity of the Wnt/β-catenin signalling pathway has been observed in osteosarcoma, and a possible interaction between TRIM37 and β-catenin has been proposed to be involved in the aberrant signalling of this pathway in other cancer types." (PMID 32961800, 2020). "High expression of TRIM37 mRNA and protein was observed in paediatric osteosarcoma tumour samples." (PMID 32961800, 2020).
renal cell carcinoma (4 papers, 2021 to 2024). "This study aimed to elucidate the impact of TRIM37 on the chemotherapy sensitivity of renal cell carcinoma (RCC) and uncover its specific molecular regulatory role." (PMID 39349442, 2024). "Additionally, TRIM37 orchestrates the progression of renal cell carcinoma by regulating histone H2Aub." (PMID 38114486, 2023). "Similarly, TRIM37 is upregulated in renal cell carcinoma and promotes the occurrence and development of renal cell carcinoma by mediating histone H2A ubiquitination resulting in activation of TGF-β1." (PMID 36249749, 2022). "Our study firstly identified the oncogenic and predictive role of TRIM37 in renal cell carcinoma." (PMID 34130705, 2021).
cervical cancer (3 papers, 2021 to 2025). A primary or metastatic malignant neoplasm involving the cervix. "TRIM37 knockdown inhibits proliferation and metastasis, and promots ferroptosis of cervical cancer cells." (PMID 40158112, 2025). "hsa_circRNA_101996 up-regulated TRIM37 expression by suppressed miR-1236-3p to promoted cervical cancer development." (PMID 34659556, 2021). "Elevated TRIM37 expression in cervical cancer tissues and cells." (PMID 40158112, 2025). "ACSL4 silencing reverses the effects of TRIM37 knockdown in cervical cancer cells." (PMID 40158112, 2025). "ATF6 activation drives TRIM37 transcription, enhancing malignancy in cervical cancer cells." (PMID 40158112, 2025).
colorectal cancer (3 papers, 2022 to 2025). A primary or metastatic malignant neoplasm that affects the colon or rectum. "Similarly, TRIM37 knockdown in colorectal carcinoma inhibited tumor growth." (PMID 35163097, 2022).
esophageal cancer (3 papers, 2020 to 2021). A primary or metastatic malignant neoplasm involving the esophagus. "The ubiquitin ligase TRIM37 has been shown to ubiquitinate adenylate kinase NEMO and activate the nuclear factor κB signaling pathway, which makes esophageal cancer cells cisplatin-resistant." (PMID 32426268, 2020).
ovarian carcinoma (3 papers, 2022 to 2026). A malignant neoplasm originating from the surface ovarian epithelium. "Here, we reported that the abnormal expression of PBK renders ovarian cancer resistant to olaparib treatment dependent on TRIM37 mediated NFκB activation." (PMID 35859118, 2022). "The MTT assay and colony formation assay both demonstrated that overexpression of TRIM37 decreases the sensitivity of ovarian cancer cells to olaparib, whereas knockdown of TRIM37 exerts the opposite effect." (PMID 35859118, 2022). "The PBK/TRIM37/NFκB axis served as a crucial signaling pathway involved in the PARPi resistance of ovarian cancer." (PMID 35859118, 2022). "In conclusion, in this study, we demonstrated that PBK directly interacts with TRIM37 to promote its phosphorylation and nuclear translocation, which subsequently activates the NFκB pathway in ovarian cancer cells." (PMID 35859118, 2022). "In conclusion, PBK confers ovarian cancer resistance to PARPi through activating the TRIM37-mediated NFκB pathway, and targeted inhibition of PBK provided the new therapy to improve PARPi treatment outcomes for ovarian cancer patients." (PMID 35859118, 2022). "We further found that NFκB activated by PBK/TRIM37 confers resistance to PARPi in ovarian cancer." (PMID 35859118, 2022). "In addition, PBK contributed to PARPi resistance of ovarian cancer through the TRIM37/NFκB axis in vitro and in vivo." (PMID 35859118, 2022). "Additionally, PBK enhanced olaparib resistance of ovarian cancer by regulating the NFκB/TRIM37 axis in vitro and in vivo." (PMID 35859118, 2022). "Firstly, we explored the function of TRIM37 in the olaparib resistance of ovarian cancer cells." (PMID 35859118, 2022). "We also pondered whether TRIM37/NFκB pathway is the key to PBK-induced olaparib resistance in ovarian cancer." (PMID 35859118, 2022). "Therefore, PBK cooperated with TRIM37 to activate the NFκB signaling pathway in ovarian cancer." (PMID 35859118, 2022).
cardiomyopathy (2 papers, 2016 to 2023). A disease of the heart muscle or myocardium proper. "Histological analysis of mouse heart revealed cardiomyopathy also in Trim37−/− mice." (PMID 27044324, 2016).